GAPLINC (gastric adenocarcinoma associated, positive CD44 regulator, long intergenic non-coding RNA)
Synonyms: TCONS_00026238; lncRNA-uc002kmd.1; RP11-838N2.4; LINC01540
Gene: Long non-coding RNA gene on chromosome 18 (3,466,200 to 3,487,049, forward strand). Ensembl gene ENSG00000266835.
Diseases named in the same sentence as GAPLINC in open-access papers:
GAPLINC is named in the same sentence as 19 diseases in open-access papers, as found by Europe PMC text mining. Sharing a sentence is not in itself a finding about the gene and the disease. The quoted sentences say what the papers report.
gastric cancer (17 papers, 2016 to 2025). A primary or metastatic malignant neoplasm involving the stomach. "For example, GAPLINC was firstly identified in gastric cancer and its upregulation was associated with shorter survival of gastric cancer patients." (PMID 28841672, 2017). "Though a growing number of long noncoding RNAs (lncRNAs), including HOTAIR, MEG3, MALAT1, H19, GAPLINC, and GClnc1, have been reported to be associated with gastric cancer tumorigenesis, the role of lncRNAs in human gastric cancer and their prognostic value are still inadequately explored." (PMID 32117443, 2020). "The overexpression of GAPLINC in gastric cancer tissues promotes hypoxia-induced tumor proliferation, migration, and invasive behavior in vivo." (PMID 40861273, 2025). "It has been shown that miR-378 regulates proliferation and cell cycle progression of gastric cancer cells by targeting GAPLINC lncRNA whereas modulates apoptosis by interacting with GAS5 lncRNA in breast cancer." (PMID 35814429, 2022). "In gastric cancer, GAPLINC promotes the invasion of gastric cancer cells by binding to miR-211–3p, which upregulates the expression of CD44." (PMID 29970131, 2018). "Initially, GAPLINC was found overexpressed in gastric cancer tissues and to serve as a poor prognostic factor in gastric cancer patients." (PMID 30177521, 2018). "GAPLINC is a novel lncRNA among aberrantly expressed lncRNAs in human gastric cancer specimens through the use of global microarray and in situ hybridization analyses." (PMID 30177521, 2018). "Recently, the prognostic value of GAPLINC expression has been suggested in gastric cancer, colorectal cancer, and bladder cancer." (PMID 30177521, 2018). "One of these lncRNAs is gastric adenocarcinoma predictive long intergenic noncoding RNA (GAPLINC), GAPLINC is overexpression and a predictive marker for metastasis and prognosis in gastric cancer." (PMID 28209170, 2017). "LncRNA-uc002kmd.1, also named GAPLINC, was reported to be associated with CD44-dependent cell invasiveness and poor prognosis of gastric cancer." (PMID 27259250, 2016). "From UCSC Genome Bioinformatics website, we found lncRNA RP11-838N2.4 was one transcript of lncRNA GAPLINC, which mediated cell migration and proliferation by forming a molecular decoy for miR-211 in gastric cancer." (PMID 27270310, 2016). "1, also known as GAPLINC, was up-regulated in GC and also displayed considerable predictive effects in the diagnosis and prognosis of gastric cancer, whereas, in our study, lncRNA-uc002kmd." (PMID 26974151, 2016). "Additionally, both HIF-1α and lncRNA GAPLINC are upregulated in gastric cancer tissues and cell lines." (PMID 40861273, 2025). "In gastric cancer cell, GAPLINC has also been found to regulate CD44-dependent cell invasiveness." (PMID 30177521, 2018). "Interestingly, RP11-838N2.4 (also known as GAPLINC) and LINC00152, two lncRNAs in green module, were both reported to be associated with invasion of gastric cancer." (PMID 28841672, 2017). "It has been reported that HOTAIR, ANRIL, GAPLINC, GHET1, H19, GAS5, and FENDRR, etc., play roles in the malignant progression of gastric cancer." (PMID 33744848, 2021). "The expression levels of LINC00853, LINC00634, LINC01535, GAPLINC, and AC017002.1 were significantly higher in gastric cancer tissues than in non-cancerous adjacent tissues (P ≤ 0.05), confirming that these five lncRNAs were differentially expressed in the EGC samples." (PMID 38586313, 2024).
gastric adenocarcinoma (7 papers, 2017 to 2025). "In addition, GAPLINC is a gastric adenocarcinoma–related lncRNA that positively regulates CD44 in various cancers." (PMID 38586313, 2024). "Gastric adenocarcinoma-associated, positive CD44 regulator, long intergenic noncoding RNA (GAPLINC), a new lncRNA, is abnormally highly expressed in many human tumors and participates in the regulation of malignant biological behavior of tumors." (PMID 34722262, 2021). "Gastric adenocarcinoma-associated, positive CD44 regulator, long intergenic noncoding RNA (GAPLINC) is a recently identified lncRNA that can actively participate in the tumorigenesis of various cancers." (PMID 34722262, 2021).
colorectal cancer (3 papers, 2018 to 2022). A primary or metastatic malignant neoplasm that affects the colon or rectum. "Moreover, several evidences showed that GAPLINC was also usually highly expressed in colorectal cancer tissues compared with adjacent normal tissues." (PMID 30177521, 2018). "Subsequent experiments found that GAPLINC promotes the expression of SNAI2 after binding to PSF/NONO, thus promoting the EMT and invasive ability of colorectal cancer cells (Table A1)." (PMID 36139386, 2022).
liver cancer (2 papers, 2023 to 2025). An epithelial or non-epithelial malignant neoplasm that arises from the liver. "We identified two lncRNAs (lncRNA-PVT1 and GAPLINC) associated with EMT in the hypoxic microenvironment of liver cancer." (PMID 40486884, 2025). "Moreover, GAPLINC was found to be involved in the regulation of epithelial-mesenchymal transition, further facilitating liver cancer invasion and migration." (PMID 36741921, 2023).
osteosarcoma (2 papers, 2018 to 2022). A usually aggressive malignant bone-forming mesenchymal neoplasm, predominantly affecting adolescents and young adults. "Survival analyses indicated that GAPLINC expression was negatively associated with overall survival, and GAPLINC high-expression was an independent risk factor in osteosarcoma patients." (PMID 30177521, 2018). "Similarly, we also found osteosarcoma patients with GAPLINC high-expression had poor overall survival compared with patients with GAPLINC low-expression, and GAPLINC high-expression was an independent risk factor for osteosarcoma patients." (PMID 30177521, 2018). "Thus, we analyzed the association between GAPLINC expression and clinicopathological characteristics in osteosarcoma clinical samples, and conducted loss-of-function study in osteosarcoma cell lines." (PMID 30177521, 2018). "In summary, these studies suggest that the CD44-miR-199a-3p axis and GAPLINC regulation are relevant regulators in the development of metastasis, tumor recurrence, and drug resistance in osteosarcoma cells mediated by CD44." (PMID 35785191, 2022). "GAPLINC overexpression in osteosarcoma was shown to correlate with advanced Enneking stage, distant metastasis, and poor outcome, providing an additional novel biomarker." (PMID 35785191, 2022). "The results of cell migration assay showed that the migration ability of osteosarcoma cell was obviously decreased when GAPLINC expression was decreased in HOS and Saos-2 cells (P<0.001)." (PMID 30177521, 2018). "In conclusion, GAPLINC expression is elevated in osteosarcoma tissues and cell lines, and correlated with the malignant status and prognosis." (PMID 30177521, 2018). "In our results, GAPLINC expression is elevated in osteosarcoma tissues and cell lines, and correlated with advanced Enneking stage, present distant metastasis, and poor histological grade." (PMID 30177521, 2018). "Then, we tried to explore the clinical significance of GAPLINC in osteosarcoma patients, and analyzed the relationship between GAPLINC expression and clinicopathological features." (PMID 30177521, 2018). "Knockdown of GAPLINC depressed osteosarcoma cell migration and invasion via inhibiting CD44 expression." (PMID 30177521, 2018). "Therefore, we supposed that GAPLINC regulates osteosarcoma cell migration and invasion through modulating CD44 expression." (PMID 30177521, 2018). "The biological function of GAPLINC in osteosarcoma cell remained unclear." (PMID 30177521, 2018). "The results of univariate Cox regression analysis suggested that advanced Enneking stage (P<0.001), large tumor size (P=0.201), present distant metastasis (P<0.001), poor histological grade (P<0.001), and high-expression of GAPLINC (P<0.001) were poor prognostic factors in osteosarcoma patients." (PMID 30177521, 2018). "In conclusion, GAPLINC may serve as a potential biomarker for predicting prognosis and developing therapy for osteosarcoma." (PMID 30177521, 2018). "Therefore, we investigated whether GAPLINC regulates osteosarcoma cell migration and invasion in a similar manner." (PMID 30177521, 2018). "The expression status and biological function of GAPLINC in osteosarcoma are still unknown." (PMID 30177521, 2018). "Levels of GAPLINC expression in HOS and Saos-2 cells were relatively higher among four osteosarcoma cell lines (MG-63, HOS, SJSA-1, and Saos-2)." (PMID 30177521, 2018). "However, the role of GAPLINC in osteosarcoma is still unknown." (PMID 30177521, 2018). "However, the expression status of GAPLINC in osteosarcoma is still unknown." (PMID 30177521, 2018). "Thus, we will further explore the regulatory mechanism between GAPLINC and CD44 in regulating osteosarcoma cell migration and invasion in a future study." (PMID 30177521, 2018).
bladder cancers (1 paper, 2018). "Subsequently, the clinical significance and biological function of GAPLINC was also explored in colorectal and bladder cancers." (PMID 30177521, 2018).
colon cancer (1 paper, 2023). "Also, GAPLINC can increase SNAI2 expression by interacting with PSF and NONO, thereby promoting colon cancer invasion." (PMID 36741921, 2023).
hepatocellular carcinoma (1 paper, 2021). A malignant tumor that arises from hepatocytes. "Subsequently, GAPLINC was found to be highly expressed in hepatocellular carcinoma and non-small-cell lung cancer and was found to promote cancer through different mechanisms." (PMID 34722262, 2021).
lung carcinoma (1 paper, 2023). "KM showed that GAPLINC is a risk factor for lung cancer patients (HR = 1.34, P=0.004)." (PMID 36741921, 2023). "A new understanding of GAPLINC's role in cancer may be provided by our results, especially in lung cancer, making it an underlying biological target." (PMID 36741921, 2023). "Our results improve the metabolism regulatory network of M2 macrophages, as well as the role of GAPLINC in cancers, especially lung cancer." (PMID 36741921, 2023).
rectal cancer (1 paper, 2022). A primary or metastatic malignant neoplasm that affects the rectum. "LncRNAs can bind to miR-34a and disrupt the regulation of miRs and target genes, including GAPLINC and SNHG7, which may increase, migrate, and invade rectal cancer cells." (PMID 35654932, 2022).
renal cell carcinoma (1 paper, 2021). "Here, we investigated the functional roles and mechanism of GAPLINC in renal cell carcinoma (RCC) development." (PMID 34722262, 2021).
viral infection (1 paper, 2024). "Higher levels of phosphorylated IRF3 were observed in GAPLINC knockdown cells than in control cells after IAV infection, indicating that depletion of GAPLINC enhanced the activation of IRF3 during the viral infection." (PMID 38227600, 2024). "To verify this, we investigated the involvement of GAPLINC in suppression of IFN response by ATG7 during the virus infection." (PMID 38227600, 2024). "It is of interest to evaluate the impact of ATG7 on the inflammatory response during viral infections, and to assess the role of GAPLINC in the regulation of inflammatory responses by ATG7 in the future." (PMID 38227600, 2024).
tumor (16 papers, 2016 to 2025). "Additionally, in hepatocellular carcinoma, increased GAPLINC expression is associated with distant metastases and tumor stages." (PMID 36139386, 2022). "HIF-1α can transcriptionally activate GAPLINC, which is highly expressed in gastric cancer tissues and promotes tumor migration and invasion behavior." (PMID 36139386, 2022). "RT-qPCR was used to detect the GAPLINC expression levels in the cells, and the results showed that the expression of GAPLINC was higher in tumor cells than in normal cells." (PMID 34722262, 2021). "Meanwhile, GAPLINC regulated tumor cell proliferation and migration through competing with CD44 for miR-211-3p." (PMID 30177521, 2018). "We then provided more evidence that the elevated expression of GAPLINC was functionally relevant to the tumor-like features of RA-FLSs." (PMID 29692777, 2018). "In these studies, GAPLINC was not only overexpressed in those tumor tissues but was also found to promote tumor cell behaviors, such as proliferation, migration, and invasive manifestations that associate with poor prognosis in patients." (PMID 29692777, 2018). "Collectively, our studies strongly suggest that elevated GAPLINC expression promote the tumor-like biologic features of RA-FLSs." (PMID 29692777, 2018). "The increased expression of GAPLINC was found to be positively correlated with larger tumor size, advanced tumor stage (T stage), advanced node stage (N stage), increased death, and shorter survival of patients with CRC by in situ hybridization analysis." (PMID 27259250, 2016). "GAPLINC was found to be expressed at a higher level in CRC tissues than in adjacent normal tissues and was significantly associated with tumor size, T stage, N stage, increased death, and shorter survival time." (PMID 27259250, 2016). "Based upon these observations of GAPLINC on tumor behaviors, the present study was performed to determine whether GAPLINC may influence the pathological phenotypes of RA-FLS." (PMID 29692777, 2018). "GAPLINC has been reported to markedly promote migration, invasive behavior, proliferation and metastasis of tumor cells, indicating that this LncRNA may be an oncogene in cancers." (PMID 29692777, 2018). "In addition, GAPLINC can function as a tumor promoter by upregulating CD44, a cell surface glycoprotein known to facilitate tumor metastasis." (PMID 27686732, 2016). "GAPLINC was overexpressed in GC tissues and promoted tumor migration and invasive behavior." (PMID 27729869, 2016). "In gastric cancer, GAPLINC (Gastric Adenocarcinoma Associated, Positive CD44 Regulator, Long Intergenic Non-Coding RNA) is a HIF-1α direct, transcriptional downstream target, and could promote invasive tumor progression." (PMID 32370770, 2020). "Additionally, GAPLINC may also promote RA-FLS tumor-like behaviors in a miR-382-5p-dependent and miR-575-dependent manner." (PMID 29692777, 2018). "Then, RT-qPCR was performed to measure the expression levels of GAPLINC, miR-135b-5p and CSF1 in tumor tissue specimens from engrafted nude mice." (PMID 34722262, 2021). "Despite reports that GAPLINC increases GC invasiveness by rescuing CD44 from miR-211, we next examined functional proteins related to tumor growth and invasiveness." (PMID 27729869, 2016). "GAPLINC regulates CD44 as a molecular sponge for miR-211-3p and enhances tumor migration and invasion." (PMID 27729869, 2016). "Moreover, we verified the expression of four lncRNAs (GAPLINC, IDI2-AS1, LINC02154, and RBPMS-AS1) in tumor and adjacent normal tissues, which was consistent with the expression of PRlncRNAs in the database." (PMID 37671354, 2023). "The lncRNA expression of GAPLINC in 539 RCC tumor tissues and 72 nontumor tissues was analyzed based on the TCGA database." (PMID 34722262, 2021).
tumor (continued). "Mechanistically, GAPLINC could serve as a decoy for miR-211-3p to restore the levels of cancer stem cell marker CD44, enhancing tumor progression." (PMID 32370770, 2020).
cancer (8 papers, 2016 to 2025). A tumor composed of atypical neoplastic, often pleomorphic cells that invade other tissues. "Compared to that in para-carcinoma tissues, both lncRNA-PVT1 and GAPLINC showed elevated expression in carcinoma tissues." (PMID 40486884, 2025). "Nevertheless, our data revealed that GAPLINC overexpression can trigger similar biological behaviours like many cancer cells." (PMID 31589383, 2019). "Previous studies have explored the role of GAPLINC in cancers." (PMID 36741921, 2023). "Phenotypic experiments proved that GAPLINC plays a role in promoting cancer through CSF1." (PMID 34722262, 2021). "Several results from cancer studies have been shown that GAPLNC can modulate the expression of Bcl‐2 by down‐regulating miR‐211.14, 21 Here, we tested this hypothesis by either silencing or overexpressing GAPLINC in HUEVC cells." (PMID 31589383, 2019).
infection (1 paper, 2024). The state of being infected such as from the introduction of a foreign agent such as serum, vaccine, antigenic substance or organism. "We observed that GAPLINC was downregulated in a virus dose- and infection time-dependent manner." (PMID 38227600, 2024).
GAPLINC also shares sentences with these, for which no sentence is quoted: breast carcinoma (1 paper); diabetes (1); lymph node metastasis (1); non-small cell lung carcinoma (1).